DTX4 (deltex E3 ubiquitin ligase 4)
Description:
Regulator of Notch signaling, a signaling pathway involved in cell-cell communications that regulates a broad spectrum of cell-fate determinations (By similarity). Functions as a ubiquitin ligase protein in vivo, mediating 'Lys48'-linked polyubiquitination and promoting degradation of TBK1, targeting to TBK1 requires interaction with NLRP4.
Synonyms: KIAA0937; RNF155
Tractability: No criterion of Open Targets' tractability assessment is met for any kind of drug.
Gene: Protein-coding gene on chromosome 11 (59,171,430 to 59,208,588, forward strand). Ensembl gene ENSG00000110042.
Subcellular location: Cytoplasm
Subcellular location (Human Protein Atlas): Vesicles
Pathways (Reactome):
Immune System: IRF3 mediated activation of type 1 IFN; IRF3-mediated induction of type I IFN; Regulation of innate immune responses to cytosolic DNA
Signal Transduction: Activated NOTCH1 Transmits Signal to the Nucleus
Gene Ontology:
Molecular function: ubiquitin protein ligase activity; ubiquitin-protein transferase activity; metal ion binding; zinc ion binding
Biological process: negative regulation of innate immune response; proteasomal protein catabolic process; proteasome-mediated ubiquitin-dependent protein catabolic process; protein K48-linked ubiquitination; Notch signaling pathway; protein ubiquitination; regulation of type I interferon production
Cellular component: centrosome; cytoplasm; cytosol; nucleoplasm
Genetic constraint (gnomAD): Loss-of-function variants: 28 observed, 52.42 expected, observed/expected ratio (o/e) 0.53, 90% interval 0.4 to 0.73. The upper end of that interval is the gene's LOEUF score, 0.73, which puts it in group 3 of 6, group 1 being the genes least tolerant of losing a copy. Missense variants: 715 observed, 815.9 expected, observed/expected ratio (o/e) 0.88, 90% interval 0.82 to 0.93. Synonymous variants: 316 observed, 324.71 expected, observed/expected ratio (o/e) 0.97, 90% interval 0.89 to 1.07.
Homologues: Orthologues: chimpanzee DTX4 (99% identical), macaque DTX4 (98% identical), mouse Dtx4 (94% identical), pig DTX4 (94% identical), dog DTX4 (93% identical), guinea pig DTX4 (92% identical), rat Dtx4 (89% identical), rabbit DTX4 (77% identical), zebrafish dtx4a (68% identical), zebrafish dtx4b (68% identical), tropical clawed frog dtx4 (40% identical). Paralogues in human: DTX1 (62% identical), DTX2 (45% identical), DTX3L (20% identical), DTX3 (15% identical).
Diseases named in the same sentence as DTX4 in open-access papers:
DTX4 is named in the same sentence as 25 diseases in open-access papers, as found by Europe PMC text mining. Sharing a sentence is not in itself a finding about the gene and the disease. The quoted sentences say what the papers report.
hepatocellular carcinoma (2 papers, 2021 to 2024). A malignant tumor that arises from hepatocytes. "DTX4 is associated with the development and metastasis of several carcinomas, such as hepatocellular carcinoma, colorectal cancer, and melanoma." (PMID 34513839, 2021). "Clinical correlation analysis showed that the mRNA levels of STAT3 were positively correlated with DTX4 in paracancerous tissue of human clinical hepatocellular carcinoma samples." (PMID 39346550, 2024).
age-related macular degeneration (1 paper, 2021). Age-related loss of vision in the central portion of the retina (macula), secondary to retinal degeneration. "WEE1, SMC2, HMGB1, RRM2, and POLA1 proteins were also observed to be involved in the progression and invasion of retinoblastoma; SLC24A2 and DTX4 in age-related macular degeneration; and EPHB6, EFNB3, and SHC1 in glaucoma." (PMID 34646884, 2021).
breast carcinoma (1 paper, 2022). "Nevertheless, significant associations with survival were observed in breast cancer patients for lower expression of DTX4 (P-value < 0.001)." (PMID 36476410, 2022).
chronic hepatitis B (1 paper, 2021). "In chronic hepatitis B, the reduction of DTX4 expression partially mediates the IFN-I signaling pathway to increase the sustenance of hepatitis B virus (HBV) and maintenance of hepatitis B surface antigen (HBsAg) in the serum." (PMID 34513839, 2021).
colorectal cancer (1 paper, 2021). A primary or metastatic malignant neoplasm that affects the colon or rectum. "DTX4 is altered by a 1.6-fold change following treatment with Pomalidomide in colorectal cancer cells." (PMID 34513839, 2021).
COVID-19 (1 paper, 2021). A disease caused by infection with severe acute respiratory syndrome coronavirus 2. "Taken together, downregulation of AGPAT2 and DTX4 supports the accumulation of LPA and free fatty acids (FAs) and alters the excess lipid storage in the inert form of triglycerides in the cellular lipid droplets, which can be seen in the COVID-19 plasma lipidome." (PMID 34659373, 2021).
lupus nephritis (1 paper, 2017). Glomerulonephritis in the context of systemic lupus erythematosus. "Although E3 ubiquitin-protein ligase DTX4 has not yet been found associated to obstructive nephropathy, using the Kidney & Urinary Pathway Knowledge Base (KUPKB,) we observed that it has been found to be induced in models of polycystic kidney disease and in a lupus nephritis model." (PMID 28249581, 2017).
pancreatic cancer (1 paper, 2018). "We measured the expression of key members of the Notch Signaling Pathway (NUMB, DTX4, DTX3L, PSEN1, APH1A, ADAM17 and EP300) in the MiaPaCa-2-miR-148a by qRT-PCR, and compared it with the basal levels of the control pancreatic cancer cell line MiaPaCa-2, expressing very low levels of miR-148a." (PMID 29464088, 2018).
polycystic kidney disease (1 paper, 2017). A usually autosomal dominant and less frequently autosomal recessive genetic disorder characterized by the presence of numerous cysts in the kidneys leading to end-stage renal failure. "Coinciding with DTX4, NAV1 expression is also induced in a model of polycystic kidney disease and is induced in vitro by the major pro-fibrotic cytokine TGFβ, potentially linking NAV1 induction to fibrosis." (PMID 28249581, 2017).
systemic lupus erythematosus (1 paper, 2021). An autoimmune multi-organ disease typically associated with vasculopathy and autoantibody production. "In systemic lupus erythematosus, the mRNA expression of DTX4 is partially modulated by circular RNA hsa_circ_0045272 and is associated with early apoptosis of Jurkat cells." (PMID 34513839, 2021).
viral infection (1 paper, 2021). "Following virus infection, USP38 is recruited to the activated TBK1 by NLRP4 and removes K33-linked ubiquitin from K670, which enables K48-ubiquitination by DTX4 and TRIF." (PMID 33808506, 2021). "DTX4 recruitment to TBK1 was shown to be dependent on the NOD protein family member NLRP4, which interacted specifically with activated (phosphorylated) TBK1 upon viral infection." (PMID 33808506, 2021).
cancer (3 papers, 2023 to 2024). A tumor composed of atypical neoplastic, often pleomorphic cells that invade other tissues. "Given the individual involvement of WNT family members cMYB and Let7a in the tumorigenic process, these findings set the basis for further studies focusing on DTX4 and its specific role in cancer regulation." (PMID 37443713, 2023). "The biological relevance of this finding towards DTX4 cellular and cancer-related functions will require further experimental evidences." (PMID 37443713, 2023). "However, to date, the most direct mechanistic evidence of DTX4 involvement in cancer relates to the regulation of the oncogenic factor TBK1 as a direct degradation target of DTX4 UbE3L activity." (PMID 37443713, 2023).
immune dysfunction (1 paper, 2025). "We observed that higher expression levels of genes like DTX4 and STING were correlated with increased proportions of non-responders to anti-PD1 therapy and elevated TIDE scores, indicating greater immune dysfunction." (PMID 40861477, 2025).
DTX4 also shares sentences with these, for which no sentence is quoted: nasopharyngeal carcinoma (2 papers); aortic stenosis (1); basal cell carcinoma (1); glaucoma (1); hepatitis B (1); latent infection (1); melanoma (1); Nephropathy (1); Obesity (1); retinoblastoma (1); soft tissue sarcoma (1); thyroid tumor (1).